CXCL16 (C-X-C motif chemokine ligand 16)
Diseases named in the same sentence as CXCL16 in open-access papers (continued):
Sharing a sentence is not in itself a finding about the gene and the disease.
oral cancer (1 paper, 2019). "Though few studies have focused on the role of CXCL16 in oral cancer, the promoting effect of CXCL16 in tumor progression was observed in other types of cancer." (PMID 30847302, 2019).
ovarian adenocarcinoma (1 paper, 2019). An adenocarcinoma that arises from the ovary. "Expression of CXCR6 and CXCL16 was also quantified by flow cytometry in normal ovarian epithelial cells (IOSE-7576), highly invasive (SKOV-3) and less invasive (OVCAR-3) ovarian adenocarcinoma cell lines." (PMID 30792527, 2019).
ovarian tumor (1 paper, 2021). "Further, the observation of proximity of CD103+ T cells to cells that express CXCL16 (the primary chemokine ligand for CXCR6) serves as additional evidence for the role of CXCR6 in Trm cell localization in ovarian tumor tissues." (PMID 34607898, 2021).
periodontal disease (1 paper, 2023). "Verification of CXCL16 function in vivo could provide strong evidence for CXCL16-dependent cholesterol influx during the pathogenesis of periodontal disease." (PMID 38036731, 2023).
periodontitis (1 paper, 2023). An acute or chronic inflammatory process that affects the tissues that surround and support the teeth. "Moreover, chemokines such as CXCL8, CXCL10, CXCL12, and CCL5 accumulate in the crevicular fluid of periodontitis patients and their source might be attributed to fibroblasts at least for CXCL2, CXCL3, CXCL8, CXCL9, CXCL10, CXCL12, and CXCL16." (PMID 37762294, 2023).
Pleural effusion (1 paper, 2025). The presence of an excessive amount of fluid in the pleural cavity. "The results showed that CXCL16 was significantly higher in the MPE of LCP than in the pleural effusion of HP, whereas BAG6 and IL-7 did not exhibit statistically significant difference." (PMID 40959273, 2025).
pneumococcal meningitis (1 paper, 2023). An acute purulent infection of the meninges and subarachnoid space caused by Streptococcus pneumoniae, most prevalent in children and adults over the age of 60. "CXCL16 was dependent on TLR2/4 and MyD88 signaling for neutrophil recruitment in the cerebrospinal fluid of patients and mice with pneumococcal meningitis." (PMID 37160878, 2023).
Primary immunodeficiency (1 paper, 2025). "Similarly, RA-related genes that interacted with CXCL16 were found to be significantly enriched with inflammation- and/or immune-related pathways, such as “Ferroptosis”, “Primary immunodeficiency” and “TNF signaling pathway” (p < 0.05, hypergeometric distribution model)." (PMID 40569958, 2025).
renal dysfunctions (1 paper, 2016). "In accordance with this report we observed a positive correlation between the post‐operative CXCL16 levels and the measured urea and creatinine levels as established markers of renal dysfunction." (PMID 26499307, 2016). "Nevertheless, elevated serum CXCL16 levels after surgery may be of particular relevance for the aggravation of disease and the development of renal dysfunctions, which further confirms the supposed key role of serum CXCL16 as useful biomarker in the setting of cardiac surgery." (PMID 26499307, 2016).
sarcoma (1 paper, 2019). A usually aggressive malignant neoplasm of the soft tissue or bone. "Matrigel invasion chamber consisting of Engelbreth-Holm-Swarm (EHS) mouse sarcoma containing laminin, collagen type IV, heparan sulfate proteoglycan, entactin was used to determine the invasive potential of OvCa cells under the chemotactic gradient of CXCL16." (PMID 30792527, 2019).
schizophrenia (1 paper, 2020). A major psychotic disorder characterized by abnormalities in the perception or expression of reality. "It is worth mentioning that some CXCL16 polymorphisms have recently been associated with schizophrenia." (PMID 33333834, 2020).
serous carcinoma (1 paper, 2019). "Expression of CXCR6 and N-terminal CXCL16 was significantly higher in serous carcinoma tissues compared to endometrioid." (PMID 30792527, 2019).
serous papillary carcinoma (1 paper, 2019). "Patients with serous papillary carcinoma with N-terminus CXCL16 higher than endometrioid appear to have some alternate mechanism like differential G- protein signaling after CXCR6 activation supporting their aggressive behavior." (PMID 30792527, 2019).
stomach adenocarcinoma (1 paper, 2021). "To investigate the possible driving mechanism of CXCL16 in promoting tumorigenesis, we used TCGA stomach adenocarcinoma cohort (STAD) to conduct on GSEA." (PMID 34345211, 2021).
thyroid tumor (1 paper, 2023). A benign or malignant neoplasm affecting the thyroid gland. "Previous studies showed CXCL16 blockage has therapeutic potential in curbing thyroid tumor growth." (PMID 37055410, 2023).
tuberculosis (1 paper, 2020). A chronic, recurrent infection caused by the bacterium Mycobacterium tuberculosis. "Studies by Lee and collaborators indicated that expression of CXCR6 on lung T cells after immunization is a marker for local protective immunity to tuberculosis and that this receptor and CXCL16 play an important role at localization of T cells." (PMID 32218590, 2020).
ulcerative colitis (1 paper, 2025). An inflammatory bowel disease involving the mucosal surface of the large intestine and rectum. "Previous studies have reported increased Veillonellaceae populations in patients with active ulcerative colitis, where their abundance was positively correlated with the pro-inflammatory chemokines CXCL16 and IL-8." (PMID 40871264, 2025).
valvular heart disease (1 paper, 2022). "During inflammatory valvular heart disease, SR-PSOX/CXCL16 is engaged in the recruitment of CD8+ T cells via activating VLA-4 and stimulating IFN-γ production." (PMID 35865542, 2022).
vasculitis (1 paper, 2014). "qRT-PCR validated the microarray analysis indicating that CXCL16 gene expression is up-regulated in HCV MC vasculitis patients [1.90 ± 0.60 (NV), 4.60 ± 0.80 (HCV MC-Vasc), 2.50 ± 0.60 (HCV), 3.10 ± 0.50 (HIV/HCV); p = 0.02 between HCV MC-Vasc and HCV viremic]." (PMID 24904592, 2014).
viral hepatitis (1 paper, 2025). An acute or chronic inflammation of the liver parenchyma caused by viruses. "Upregulation of CXCL16 was found in viral hepatitis, MASLD, and ALD, where it promoted fibrosis development." (PMID 41373861, 2025).
tumor (329 papers, 2008 to 2026). "Survival analysis, which incorporated scoring for CXCL16 and five signature genes specifically overexpressed in tumor cells, discovered a significant association between high CXCL16 expression and poor prognosis in GC patients." (PMID 40452847, 2025). "CXCR6-deficient T-cells or those treated with CXCL16-blocking Abs show impaired retention and reduced local anti-tumour activity." (PMID 40361472, 2025). "Transcriptome analysis of high-grade urothelial carcinomas revealed that CXCL16 expression is significantly associated with PD-L1-mediated immune evasion, indicating its role in promoting tumor immune tolerance and progression." (PMID 39409924, 2024). "Tumor-associated macrophages (TAMs) coculturing with OC cells enhance cisplatin resistance via increasing CXCL16 expression." (PMID 38544837, 2024). "Among other notable DEGs, PD-L1+ clusters were also defined by high expression of many transcripts encoding for chemokines that have been shown to be released by suppressive tumor-associated neutrophils such as Ccl2, Ccl3, Ccl4, Ccl5, Ccl12, Ccl17, and Cxcl16." (PMID 39392875, 2024). "In fact, the role of CXCL16 in tumorigenesis is closely associated with tumor-correlated cells, which suggests that CXCL16 acts on tumor-associated cells and is thus secreted into the tumor microenvironment." (PMID 37272931, 2023). "As seen in PCa, primary breast cancer tumors recruit CXCR6 expressing MSCs via CXCL16, and the tumor-associated MSCs then secrete other chemokines, such as CCL5 and CXCL10, that promote invasion and metastasis." (PMID 37025604, 2023). "Tumor-associated macrophages promote the cisplatin resistance of OC cells by enhancing WTAP-mediated N6-methyladenosine RNA methylation via the CXCL16/CXCR6 axis." (PMID 37272931, 2023). "In some cancers, such as colorectal and renal cancer, CXCL16 is associated with tumor-infiltrating lymphocytes and good prognosis." (PMID 37025604, 2023). "The mean percentages of tumor-associated CXCL16+ CD45+ cells among all the CD45+ cells decreased from 8.5% in IgG to 2.1% in CXCL16 NAb group." (PMID 37055410, 2023). "In PCa, mesenchymal stem cells migrated into the tumor site through the chemotactic effects of CXCL16, which was further transformed into cancer-associated fibroblasts in TME, promoting the EMT and metastasis of PCa." (PMID 36275733, 2022). "The involvement of CXCL16 in tumorigenesis is closely related to the tumor-associated cells on which it acts and from which this chemokine is secreted into the tumor microenvironment." (PMID 33800554, 2021). "There are indications that CXCL16 is also involved in the functioning of tumor-associated neutrophils (TAN)." (PMID 33800554, 2021). "As the high expression level of CXCL16 was associated with distance metastasis in patients with primary GC, we examined the effects of CXCL16 on tumor metastatic colonization." (PMID 34345211, 2021). "On the other hand, the ligands of CXCR3, and CXCL14 and CXCL16, cause tumor infiltration by anticancer tumor-infiltrating lymphocytes (TILs) and thus show anticancer properties." (PMID 33467722, 2021). "CXCL16 is important for the functioning of tumor-associated macrophages (TAM)–monocytes polarized into macrophages by factors found in the tumor microenvironment." (PMID 33800554, 2021). "A previous study demonstrated CXCL16 as a potential mediator of tumor associated macrophages (TAMs), supporting TAM-mediated cell migration and the invasion potentials of PTCs9." (PMID 31527616, 2019). "CXCR6 stimulates the conversion of mesenchymal stem cells into cancer-associated fibroblasts, facilitating tumor metastasis, whereas CXCL16 promotes tumor proliferation and migration." (PMID 27618112, 2016). "Metalloproteinases ADAM-10 and ADAM-17, which cleave membrane CXCL16 to generate soluble CXCL16, have also been linked to increased tumor burden." (PMID 27471636, 2016).
tumor (continued). "In order to investigate the possibility of a more general association between CXCL16 and inflammation-associated cancer, we studied the expression of CXCL16 in 582 cases of cancer covering 12 tumor types." (PMID 19690611, 2009). "Cancer cells’ soluble (S)-CXCL16 secretion causes a positive feedback loop, either directly through interactions with PCa cells or indirectly by creating an inflammatory milieu that promotes the growth of tumor cells." (PMID 38745115, 2024). "Abnormal expression of CXC motif chemokine ligand 16 (CXCL16) has been demonstrated to be associated with tumor progression and metastasis, served as a prognostic factor in many cancers, with higher relative expression behaving as a marker of tumor progression." (PMID 34345211, 2021). "Another promising chemokine is CXCL16, which causes tumor infiltration by anticancer TILs." (PMID 33467722, 2021). "To investigate how determining CXCL16 mRNA expression levels in lymph nodes could be clinically relevant for predicting tumor recurrence after surgery, we calculated the hazard risk ratio using Cox regression analysis." (PMID 31752131, 2019). "While these beneficial effects may be related to transmembrane CXCL16, soluble CXCL16 has been linked to increased tumor metastasis." (PMID 27471636, 2016). "Elevated CXCL16 levels within the tumor niche also promote the conversion of stromal cells into cancer-associated fibroblasts (CAFs) in both preclinical models and patient samples of ARID1A-deficient EC." (PMID 41957354, 2026). "Among the secreted factors, CXCL16 emerges as the predominant chemokine, promoting epithelial-to-mesenchymal transition and enhancing tumor cell invasiveness." (PMID 41957354, 2026). "This conclusion is also supported by a corresponding increase in the ligands for CXCR3, CCR5 (e.g., CXCL9, CXCL10, CCL5) in both tumor and liver supernatants after treatment, whereas CXCR6 ligand (CXCL16) is higher only in the tumor." (PMID 41415437, 2025). "We further validated these findings using scRNA-Seq of tumor tissues from patients with PC, demonstrating that those with higher CXCL16 expression were more sensitive to gemcitabine treatment." (PMID 40924501, 2025). "In the TME or during chronic infections, CXCL16 was often highly expressed in tumor tissues, infected areas, or sites of inflammation." (PMID 40394037, 2025). "Primary BAs increase CXCL16 expression, favoring a tumor suppressor microenvironment, whereas secondary BAs have the opposite effect." (PMID 39851512, 2025). "Armoring CAR T-cells with CXCR6, the receptor for CXCL16, led to increased anti-tumor efficacy and prolonged the survival of treated mice." (PMID 41019052, 2025). "Using SOAR, we found that CXCL16/SPP1 macrophage polarity characterizes the coordination of immune cell polarity in the tumor microenvironment." (PMID 40498826, 2025). "In the current study, we identified CAFs as the main drivers of the CXCL16–CXCR6 axis in MPE, attributed to their elevated CXCL16 expression, aligning with the well-known secretory characteristics of CAFs in tumor environment." (PMID 41310104, 2025). "Initially, tumor cells secrete CXCL16 to recruit Tc17 cells, thereby enhancing their accumulation within the TME." (PMID 40452847, 2025). "In our current study, we have demonstrated through various approaches that GC tumor cells highly express CXCL16, while Tc17 cells, a subset of T cells, highly express CXCR6." (PMID 40452847, 2025). "The results indicated that Tc17 cells adjacent to CXCL16+ tumor cells exhibited higher CXCR6 expression." (PMID 40452847, 2025). "These myCAFs exhibited strong interactions with cytotoxic T/NK cells through the ICAM1, CD55, CXCL13, and CXCL16 signaling pathways, suggesting a potential contribution to tumor regression." (PMID 40107247, 2025). "Multiple cancer types exhibit aberrant expression of chemokine ligand 16 (CXCL16), which serves as a prognostic factor and indicator of tumor progression." (PMID 40375334, 2025).
tumor (continued). "CXCL16 exhibits a multifaceted role in tumour biology, functioning as either a tumour-promoting or tumour-suppressing factor depending on the cellular and microenvironmental context." (PMID 40869222, 2025). "We also annotated CXCR6+ regulatory T cells (Tregs) which potentially move toward the tumor site by CXCL16, shaping the immunosuppressive TME." (PMID 40776410, 2025). "To functionally characterize this antibody library, we performed targeted screening against CXC motif chemokine ligand 16 (CXCL16), a crucial chemokine involved in inflammatory pathogenesis and tumor microenvironment regulation." (PMID 40930253, 2025). "RT triggers the release of chemokines (CXCL10 and CXCL16) from tumor cells to recruit effector T cells to the tumor site, thereby enhancing the anti-tumor immune response." (PMID 40141437, 2025). "Recent studies have highlighted the activation of the CXCL16/CXCR6 axis as a pivotal element in T cell-mediated tumor immunity, which is consistent with the increased proportion of CXCR6-high T cells we detected in interactions with M1-like TAMs." (PMID 41031375, 2025). "Last, but not least, there is growing evidence that CXCL9/CXCL10/CXCR3 and CXCL16/CXCR6 are involved in tumor pathogenesis, so they probably represent pleiotropic chemokines at the crossroads of immunity and carcinogenesis." (PMID 41373861, 2025). "Reports have indicated that CXCR6 expression is elevated in some T cells, and these CXCR6+ T cells are recruited into tumor tissues through a CXCL16 gradient." (PMID 40452847, 2025). "The CXCL16, a multifunctional chemokine, exerts dual influences on both inflammatory responses and tumor progression, It also contributes to the acceleration of atherosclerotic plaque formation and development." (PMID 40297588, 2025). "CXCL16 can also act as a chemotactic agent for tumor-infiltrating T lymphocytes to create a microenvironment enhancing cancer progression." (PMID 38172124, 2024). "Taken together, the CXCL16/CXCR6 axis is important for effector T cell enrichment in the tumor microenvironment of various cancers." (PMID 38928238, 2024). "In an in vitro immunohistochemistry study, more tumor-infiltrating lymphocytes were recruited by colorectal cancer cells that upregulated CXCL16." (PMID 38928238, 2024). "In the context of CAR-T cells, where trafficking is a major challenge, overexpressing CXCR6 in CAR-T cells improves their trafficking when CXCL16 is highly expressed on tumor cells." (PMID 38509063, 2024). "The expression of CXCL16 by tumor cells traps CXCR6+ effector T cells in the tumor mass, limiting the generation of memory T cells by sequestering their precursors in the tumor." (PMID 38509063, 2024). "We observed that CXCL16+ glyCAF were enriched at the tumor margin of immune-excluded STS tumors, but their frequency was lower in highly immune-infiltrated tumors." (PMID 38509063, 2024). "GlyCAF rely on GLUT1-dependent expression of CXCL16 to impede cytotoxic T-cell infiltration into the tumor parenchyma." (PMID 38509063, 2024). "CXCL16 is characterized as a proangiogenic cytokine and acts as an important angiogenic factor in the tumor microenvironment." (PMID 38172124, 2024). "Irradiation stimulates tumor cells to release chemokines (CXCL16 and CXCL10) that activate T cells and increase their recruitment into the tumor." (PMID 39199577, 2024). "In vitro studies have shown that CXCL16 expression induces tumor cell and mesenchymal stem cell migration, promoting cancer metastasis to the bone." (PMID 39550375, 2024). "Tumor-derived CXCL16 interacts with MSC CXCR6 to modify MSCs into CAFs, which release significant amounts of CXCL12." (PMID 38745115, 2024). "CXCL16 is indicated to play a critical role in MSC-boosted tumor metastasis by facilitating MSC recruitment and conversion to CAFs that secrete CXCL12 to regulate EMT in tumor cells." (PMID 38951845, 2024).